MMP1 (matrix metallopeptidase 1)
Diseases named in the same sentence as MMP1 in open-access papers (continued):
Sharing a sentence is not in itself a finding about the gene and the disease.
chronic hepatitis C (5 papers, 2009 to 2026). "A study assessing serum fibrosis biomarkers for staging fibrosis in chronic hepatitis C patients found that only MMP-1 and PIIINP were independently associated with fibrosis, leading to the development of the MP3 score based on their combination." (PMID 40572790, 2025). "MMP-1 serum levels were found to be inversely related to the disease severity in patients with chronic hepatitis C infection." (PMID 32414178, 2020). "(2013) for chronic hepatitis C patients included variables such as hyaluronic acid, TGF-β1, α2-macroglobulin, Matrix Metalloproteinase (MMP)-2, apolipoprotein-A1, urea, MMP-1, alpha-fetoprotein, haptoglobin, red blood cell count, hemoglobin, and TIMP-1." (PMID 41551471, 2026). "Based on the results, the combination of col-III/MMP-1 ratio (CMR), alpha-fetoprotein (AFP), aspartate aminotransferase (AST)/alanine aminotransferase (ALT) ratio and platelet count has been suggested for F2–F4 staging of fibrosis in patients with chronic hepatitis C infection." (PMID 32414178, 2020).
diabetic foot ulcers (5 papers, 2008 to 2025). "The MMP-1/TIMP-1 ratio is a predictor of wound healing in diabetic foot ulcers." (PMID 18387077, 2008). "It was reported previously that MMP1, MMP2 and MMP9 are significantly over-expressed in diabetic fibroblasts and are important determinants of diabetic foot ulceration morbidity and exacerbation." (PMID 28423369, 2017). "Mechanisms could include the dampening of the pathologically excessive levels of collagenases (MMP-1 and MMP-8) and gelatinases (MMP-2 and MMP-9) that have been observed in biopsies of diabetic foot ulcers, compared to the levels of these proteinases seen in normal posttraumatic wounds." (PMID 27190999, 2016).
fibrosarcoma (5 papers, 2015 to 2024). A malignant mesenchymal fibroblastic neoplasm affecting the soft tissue and bone. "Previous studies have suggested that MMP1 can be epigenetically regulated; a methyltransferase inhibitor, 5-aza-2′-deoxycytine, has been shown to induce a decrease in its protein expression in a human fibrosarcoma cell line." (PMID 35267540, 2022). "Specifically, it inhibits MMP-1, MMP-3, MMP-7, MMP-9, and MMP-14, which hinders the expansion of HUVECs and the activated process of proMMP-2 regulated by MMP-14 in human fibrosarcoma cells." (PMID 38611849, 2024). "Previous studies have also shown suppression of MMPs in response to IFN-γ, such as MMP-9, which like MMP-1 and MMP-3, also contains AP-1 sites (two) and putative SBEs58–60, and has been shown to be repressed following IFN-γ treatment in astrocytes, fibrosarcomas, and monocytes." (PMID 28819304, 2017).
Inguinal hernia (5 papers, 2017 to 2023). Protrusion of the contents of the abdominal cavity through the inguinal canal. "Significantly higher levels of MMP-1, -2, and -9 in the transversalis fascia have been shown in patients with inguinal hernias versus controls." (PMID 29018803, 2017). "On the other hand, there is a larger body of evidence supporting the role of MMPs (matrix metalloproteinases) in inguinal hernias, as multiple articles have consistently shown increased levels of MMP-1, 2, 9, 12, and 13 in both the serum and fascia of patients with inguinal hernias." (PMID 37509159, 2023). "The relationship of metallopeptidase genes, such as MMP1 and MMP13, with inguinal hernias in humans has already been verified." (PMID 32379844, 2020). "For instance, MMPs (e.g., MMP‐1, MMP‐2, MMP‐9, MMP‐13) appear to be involved in inguinal hernia or recurrent inguinal hernia development." (PMID 31588690, 2019). "Significantly lower collagen subtype 1:3 ratio in skin has been shown for individuals with inguinal hernias without any differences between hernia subtypes or MMP-1/13 levels." (PMID 29018803, 2017).
liver disease (5 papers, 2009 to 2026). "Thus, glycyrrhizin used for the treatment of hepatic diseases and itching dermatitis was shown to possess an anti-fibrotic effect in SSc dermal and lung fibroblasts via downregulation of Dnmt1, upregulation of Fli1, and induction of MMP1 gene expression via an ERK1/2-dependent mechanism." (PMID 36768203, 2023). "TNFα also modulates several matrix metalloproteinases that are involved in liver injury, repair, and remodeling, with MMP1 and MMP9 the most relevant MMPs with regards to liver disease." (PMID 26506376, 2015). "Also, five proteins (HSP90B1, Protein S100-A9 [S100A9], MMP1, matrix metalloproteinase-9 [MMP9], and CSF3) in the IL17 signaling pathway are in phase III clinical trials for treating solid tumors and have the potential to treat liver diseases." (PMID 37209815, 2023).
lung squamous cell carcinoma (5 papers, 2014 to 2024). "Several matrix metalloproteases are regulated in NSCLC including MMP1, which is up regulated in both adenocarcinomas and squamous cell lung cancer." (PMID 25249545, 2014).
nasopharyngeal carcinoma (5 papers, 2016 to 2022). A carcinoma arising from the nasopharyngeal epithelium. "The promoter polymorphisms of MMP-1 have also been implicated in increased susceptibility of nasopharyngeal carcinoma." (PMID 28672814, 2017). "The fact that gallic acid inhibits the MMP-1 activity may provide a valuable pharmacological choice for treatment of nasopharyngeal cancer." (PMID 28672814, 2017). "Fra-1 reportedly regulates the high expression of MMP-1,2,9 in nasopharyngeal carcinoma." (PMID 27626695, 2016).
scleroderma (5 papers, 2012 to 2021). Scleroderma is a rare autoimmune connective tissue disorder characterized by abnormal hardening of the skin and, sometimes, other organs. "Addition of HGF to fibroblast cultures of scleroderma patients significantly decreased collagen production and increased MMP-1 expression and activity." (PMID 25332857, 2014). "Indeed, others have shown that AHR plays a role in controlling MMP1 production in scleroderma and periodontal ligament cells." (PMID 32439897, 2020). "Another in vivo study revealed that MMP-1 expression in dermal fibroblasts was markedly increased, and the levels of type I and type III collagen were significantly decreased in the lesions of scleroderma patients after high-dose UVA1 irradiation." (PMID 23554742, 2012).
acne (4 papers, 2010 to 2025). An inflammatory process of the sebaceous glands which is characterized by comedones, nodules, papules and/or pustules on the skin. "The core targets - EGFR, MMP1, MMP2, MMP9, and MMP13 - that directly participate in the relaxin signalling pathway are useful in managing acne by targeting these core targets." (PMID 39347283, 2024). "Specifically, the modulation of EGFR and various MMPs (MMP1, MMP2, MMP9, and MMP13) through the relaxin signalling pathway appears to be a pivotal mechanism by which P. pterocarpum exerts its anti-acne effects." (PMID 39347283, 2024). "Among the 21 common targets of P. pterocarpum and acne, five targets - EGFR, MMP1, MMP2, MMP9, and MMP13 - were selected as the core targets because of their direct involvement in the relaxin signalling pathway." (PMID 39347283, 2024). "Clinical data indicate high levels of MMP-1 and MMP-13 in the facial sebum of acne patients." (PMID 39942620, 2025). "Various MMP1 and MMP2 expression levels may play a role in the formation of different types of acne lesions." (PMID 39347283, 2024). "Moreover, the prominent induction of genes, such as PTGS2, CXCL8, IL6, IL1B, matrix metalloproteinase 1 (MMP1) and NLRP3, even raised the possibility that EGF and PA may be involved in the pathogenesis of acne." (PMID 34025636, 2021).
angina (4 papers, 2009 to 2024). "Yet, the previous report showing that plasma concentration of CT is elevated in patients with unstable angina compared with those with stable angina supports our hypothesis that CT-1 induces MMP-1 in vascular endothelium and contributes to the plaque instability in patients with unstable angina." (PMID 23935888, 2013).
Aortic dissection (4 papers, 2009 to 2024). Aortic dissection refers to a tear in the intimal layer of the aorta causing a separation between the intima and the medial layers of the aorta. "It has been reported that when aortic dissection occurs, the serum levels of MMP1, MMP2, MMP3, MMP8, and MMP13 are increased, and the expression of MMP9 in the cytoplasm of smooth muscle cells in the aortic wall is enhanced." (PMID 35463768, 2022). "Significantly lower levels of MMP-1 were found in healthy controls compared to all groups of patients (1.1 ± 0.38 ng/ml versus 2.97 ± 0.68 in acute aortic dissection, 3.09 ± 0.98 in chronic dissection, 3.16 ± 0.51 in thoracic aortic aneurysm and 4.58 ± 1.04 in acute myocardial ischemia, p < 0.05)." (PMID 19886986, 2009).
Autoimmunity (4 papers, 2011 to 2025). The occurrence of an immune reaction against the organism's own cells or tissues. "Emerging therapies targeting MMP-1 and associated G protein-coupled receptors highlight shared pathogenic mechanisms between autoimmunity and oncogenesis." (PMID 40567613, 2025). "Of interest, MMP-1 can be released by macrophages, monocytes and monocyte-derived DC, and alteration of its expression has been recently associated with autoimmunity phenomena." (PMID 21586124, 2011). "We also found elevated levels of MMP1 in CSF and CSF HS and HA were positively associated with NMO, MS and autoimmune GFAP astrocytopathy." (PMID 34367165, 2021). "While this study does not establish whether the diminished production of MMP-1 that we have observed is due to T cell autoimmunity to CI or due to a costimulatory effect of CI on activated T cells, we favor an antigenic role of CI in triggering production of cytokines." (PMID 22367096, 2012).
bladder tumour (4 papers, 1998 to 2017). "In this study we will focus on MMPs, which are described in the literature to have an impact in bladder tumour carcinogenesis: the collagenase MMP1, the stromelysin MMP3, and the gelatinases MMP2 and MMP9." (PMID 16901349, 2006). "This study showed that MMP2, MT1-MMP, and MMP28 were very highly expressed in bladder tumour samples and MMP1, 7, 9, 11, 15, 19, and 23 were also highly expressed." (PMID 16901349, 2006). "MMP1 protein was detected in urine from patients with bladder tumours, with a significant increase in concentration with increased stage and grade of tumour." (PMID 9683296, 1998). "The effect of epidermal growth factor (EGF) on matrix metalloproteinase-1 (MMP1) production in two human bladder tumour cell lines, RT112 and RT4, has been investigated." (PMID 9683296, 1998). "MMP1 urine concentrations may therefore be a useful prognostic indicator for bladder tumour progression." (PMID 9683296, 1998). "In total, five articles investigating four different MMPs types (MMP1, MMP7, MMP9, and MMP11) reported a relationship between abnormal levels of MMPs and bladder tumor progression." (PMID 28427222, 2017).
bronchiectasis (4 papers, 2013 to 2024). Segmental, irreversible dilation of the bronchial tree resulting in the accumulation of secretions which leads to obstruction. "There was a higher association for having either one or two copies of MMP-1(-1607G) polymorphisms in bronchiectasis patients with more than one lobe involved compared to those with only one lobe involved (81.5% vs. 43.8%, p = 0.0003)." (PMID 23776649, 2013). "Mostly important, the serum level of MMP-1 in our bronchiectasis patients with at least one G allele of MMP-1 polymorphism was upregulated compared to that of 2G/2G genotype." (PMID 23776649, 2013). "Bronchiectasis patients with at least one MMP-1 (-1607G) allele showed increased tendency for hospitalization." (PMID 23776649, 2013). "By contrast, our results demonstrated that bronchiectasis patients with one or two copies of G allele of MMP-1 polymorphism tended to have a greater extent of lung destruction, a rapid decline of pulmonary function and reduced exercise tolerance." (PMID 23776649, 2013). "The frequency of MMP-1(-1607G) allele was significantly higher in patients with bronchiectasis than normal subjects (70.8% vs 45.1%, p<0.01)." (PMID 23776649, 2013). "The most common genotype of MMP-1 polymorphism was 1G/2G in bronchiectasis patients (58.4%), and 2G/2G (54.9%) in the controls." (PMID 23776649, 2013). "We have demonstrated that the frequency of MMP-1(-1607G) polymorphism was associated with greater extent of disease and more lung destruction in patients with bronchiectasis." (PMID 23776649, 2013). "Allele frequencies of MMP-1(-1607G) genotype between the bronchiectasis patients and controls are also shown." (PMID 23776649, 2013). "Association of MMP-1 (-1067GG) polymorphisms and number of involved lobe in bronchiectasis." (PMID 23776649, 2013). "The frequency of 1G allele of MMP-1 polymorphism in our bronchiectasis patients, especially those with multilobar involvement, was significantly different from that of healthy controls, indicating that the polymorphism of MMP-1 promoter is associated with the risk for developing bronchiectasis." (PMID 23776649, 2013). "In patients with bronchiectasis, the presence of Rothia was found to be negatively correlated with pro-inflammatory factors such as IL-8, IL-1β, MMP-1, MMP-8, and MMP-9 in sputum." (PMID 38779669, 2024). "In a cohort of adults with bronchiectasis, the abundance of Rothia species was negatively correlated with pro-inflammatory markers (interleukin (IL)-8 and IL-1β) and matrix metalloproteinase (MMP)-1, MMP-8 and MMP-9 in sputum." (PMID 36403054, 2022). "The results demonstrated that bronchiectasis patients who have at least one -1607G of MMP-1 have higher TGF-β1 levels than those with bronchiectasis with 2G/2G genotype or normal subjects." (PMID 23776649, 2013). "Further studies with a larger cohort of patients may be warranted to elucidate the possible involvement of MMP-1 in the pathogenesis of bronchiectasis." (PMID 23776649, 2013). "This is the first report to address the influence of MMP-1 polymorphisms on lung function and airway destruction in non-CF bronchiectasis patients." (PMID 23776649, 2013). "Serum levels of pro-MMP-1, active MMP-1 and TGF-β1 were significantly increased in patients with bronchiectasis with 1G/1G and 1G/2G genotype compared with 2G/2G genotype or normal subjects." (PMID 23776649, 2013). "Collagenase (MMP-1) and neutrophil-type collagenase/MMP-8 are found in broncholaveolar lavage fluid from patients with bronchiectasis." (PMID 23776649, 2013). "The serum levels of MMP-1 and TGF-β1 were higher in bronchiectasis patients with 1G/2G and 1G/1G genotype of MMP-1 polymorphism." (PMID 23776649, 2013).
Cirrhosis (4 papers, 2014 to 2024). A chronic disorder of the liver in which liver tissue becomes scarred and is partially replaced by regenerative nodules and fibrotic tissue resulting in loss of liver function. "Our data showed that the mRNA and protein levels of TIMP-1 were remarkedly increased and the levels of MMP-1 were significantly decreased in the CCl4-induced cirrhosis liver group." (PMID 32928296, 2020).
Crohn disease (4 papers, 2023 to 2025). A gastrointestinal disorder characterized by chronic inflammation involving all layers of the intestinal wall, noncaseating granulomas affecting the intestinal wall and regional lymph nodes, and transmural fibrosis. "The most frequently analyzed metalloproteinases in Crohn’s disease are: MMP-1, MMP-3, MMP-7, MMP-8 and MMP-9." (PMID 37895443, 2023). "MMP-1, MMP-3, MMP-7, MMP-8 and MMP-9 are biomarkers of Crohn’s disease." (PMID 37895400, 2023).
cutaneous melanoma (4 papers, 2019 to 2024). A primary melanoma arising from atypical melanocytes in the skin. "Pancreatic adenocarcinoma (PAAD) showed the highest number (9 out of 10) of upregulated biomarkers, while skin cutaneous melanoma (SKCM) had only one upregulated biomarker—MMP1." (PMID 36428623, 2022).
ductal carcinoma (4 papers, 2006 to 2021). "We also found association between ductal carcinoma histology and MMP1 expression; however, in our study, this association was statistically significant only for tumor associated stroma." (PMID 24972610, 2014). "Nevertheless, of the total number of patients analyzed with cancer, we identified that MMP-1 staining intensity and MMP3 staining percentage and intensity were higher in postmenopause patients, in those with positive hormone receptors, and in the histological ductal carcinoma type." (PMID 34445715, 2021).
exfoliation syndrome (4 papers, 2009 to 2025). An autosomal dominant disorder caused by mutations in the LOXL1 gene, encoding lysyl oxidase homolog 1. "As for the MMP1 −1607 1G/2G polymorphism, a Greek study showed a trend for association with exfoliation syndrome." (PMID 20808730, 2010). "Our study provided some evidence of a possible role of the MMP1 variant in the development of exfoliation syndrome in Greek patients." (PMID 20038976, 2009). "In summary, our study provided some evidence of a possible significant role of the MMP1 variant in the development of exfoliation syndrome in Greek patients." (PMID 20038976, 2009). "Remarkably, investigating the association between exfoliation syndrome and XFG and the MMP1 −1607 1G/2G polymorphism, Tsironi and coworkers reported an allele contrast of borderline significance for exfoliation syndrome (OR=1.47; 95%CI: 1.03–2.10; p=0.04), but not for XFG." (PMID 20808730, 2010).
gallbladder cancer (4 papers, 2021 to 2023). "A study highlighted NEDD4 as an invasion-associated molecule in gallbladder carcinoma and demonstrated that at the transcriptional level NEDD4L regulates MMP-1 (Matrix metalloproteinase-1) and MMP-13 expression, which is overexpressed at an early stage of tumor invasion in various malignant tumors." (PMID 36293239, 2022). "In addition, NEDD4L overexpression may lead to gallbladder cancer invasion by decreasing the transcription of MMP1 and MMP13." (PMID 38027016, 2023). "Moreover, the upregulation of NEDD4L enhances the transcription of MMP1 and MMP13, leading to aggressive gallbladder cancer." (PMID 38027016, 2023).
Hepatitis (4 papers, 2009 to 2024). Inflammation of the liver. "Moreover, our discovery that PGE2 induces MMP1 expression to increase sCD46 release from HepaRG cells strengthens the connection between elevated sCD46 levels in blood and liver inflammation." (PMID 39698100, 2024). "Therefore, MMP-1 may play a key role in hepatitis onset and can thus be used as an indicator of cell repair capacity." (PMID 34611503, 2021).
Hyperglycemia (4 papers, 2018 to 2024). An increased concentration of glucose in the blood. "Additionally, the downregulation of IGF1 via the ETS1/MMP1 pathway in this prediction model contributed to hyperglycemia, which has been validated by studies on the b-cells of diabetic transgenic mice." (PMID 39125657, 2024). "Specifically, P38MAPK is involved in the deposition of matrix metalloproteinase 1 (MMP-1), while ERK moderates the production of type 1 collagen in the setting of hyperglycemia." (PMID 35955802, 2022).